INS (insulin)
Diseases named in the same sentence as INS in open-access papers (continued):
Sharing a sentence is not in itself a finding about the gene and the disease.
diabetes (continued). "In addition, there is no convincing evidence for a carcinogenic role of any insulin derivative currently used in therapy for diabetes." (PMID 26641266, 2015). "Participants with diabetes were on average older, had greater BMI, and demonstrated several metabolic characteristics of type 2 diabetes, including low HDL cholesterol, increased fasting insulin and elevated CRP levels when compared to participants without diabetes." (PMID 25607823, 2015). "Insulin plus melatonin restored the body temperature rhythm whereas insulin alone resulted less efficient; melatonin alone did not restore any of the parameters studied; however, when supplemented close to diabetes onset, it maintained the temperature rhythmicity." (PMID 25960780, 2015). "In line with this trend, we have demonstrated the clinical relevance of GA in type 2 diabetes mellitus (T2D) with insulin secretory dysfunction rather than insulin resistance, fluctuating or poorly controlled glycemic excursions, and progressing atherosclerosis." (PMID 26484352, 2015). "However, when comparing diabetes patients with and without fractures, poor glycemic control (threshold of HbA1C 7 % (53 mmol/l)), longer disease duration, and insulin use were not significantly different." (PMID 25648962, 2015). "In addition, we evaluated the incidence of diabetes, degree of insulitis, serum insulin, hepatic glutathione and tolerance test glucose in non-obese diabetic (NOD) mice." (PMID 26783951, 2015). "As insulin is one of the growth factors involved in cancer development, these effects could contribute to the reduced cancer rate in dialyzed ESRD patients with diabetes." (PMID 25965806, 2015). "While QoL is undoubtedly important, we are concerned that the paediatric diabetes QoL questionnaires validated to date may not be sufficiently sensitive to identify the ways in which these modes of insulin delivery impact QoL differently." (PMID 25873144, 2015). "Moreover, serum levels of mouse insulin became negligible after induction of diabetes without any change throughout the observation period." (PMID 26064925, 2015). "However, cells that co-express insulin and glucagon were never found in our samples from controls or diabetics." (PMID 26057531, 2015). "Therefore, our aim is to compare the effects of high and low AGE diets, followed for 2 weeks, on direct measures of insulin sensitivity and insulin secretion in healthy yet overweight or obese individuals without diabetes." (PMID 26223897, 2015). "Age, duration of diabetes, history of previous CHD, tobacco smoking, type of ACS, baseline antidiabetic treatment, cardiovascular drug use, baseline VO2 peak, baseline ventilatory threshold, insulin use during CR and mean insulin dose in the insulin-treated patients were similar in the 2 groups." (PMID 26152221, 2015). "Moreover, LOF of COX2 may increase insulin secretion, and GOF of COX2 may induce insulin dependent diabetes mellitus (IDDM)." (PMID 25946000, 2015). "Therefore, most of the participants had “diet only” treatment without medications (31%, 26/84) or were using one diabetes medication but not insulin (42%, 35/84)." (PMID 25648130, 2015). "Generic (Short-Form 36 Health Survey - SF-36) and specific (Problem Areas in Diabetes - PAID) HRQoL questionnaires, Beck Depression Inventory (BDI), clinical, laboratorial and socio-demographic data were recorded on baseline and 6 months after the beginning of insulin treatment." (PMID 26110026, 2015). "We may conclude that one uniform portal is not suitable for all patients and we should consider dividing a diabetes web portal immediately after the entrance in two parts: one for patients who are injecting insulin and another for patients who do not." (PMID 26086272, 2015).
diabetes (continued). "Suppressed levels of intracellular magnesium has been reported in patients with diabetes, and it has been suggested that circulating blood glucose independent of insulin levels, is a physiologic determinant of cellular ion hemostasis, suppressing intracellular free magnesium." (PMID 25237327, 2014). "Asinclusion criteria, children and adolescents could not: present any concomitantdisease (except for diabetes), make use of any medication (except for insulin),smoke, drink, or eat abusive amounts of food." (PMID 25119762, 2014). "In conclusion, our data suggest that alcohol consumption may improve insulin sensitivity and reduce the risk of type 2 diabetes and type 2-like LADA alike but has no beneficial effect on diabetes-related autoimmunity." (PMID 25117461, 2014). "Regarding diabetes type, as information on this predictor was lacking we included insulin use in our candidate predictor list, which may have been a weaker predictor." (PMID 24594735, 2014). "Pancreatic β-cells express the molecular clock proteins controlling circadian rhythm of insulin secretion and impairment of some member of the clock genes such as circadian locomotor output cycles kaput (CLOCK) and brain and muscle ARNT-like 1 (BMAL1), leading to hypoinsulinemia and diabetes." (PMID 24672804, 2014). "The medications used for diabetes treatment for patients with DM included metformin (16.5%), sulfonylureas (74.9%), thiazolidinediones (9.9%), α-glucosidase blockers (9.5%), non-sulfonylurea insulin secretagouge (6.5%), and insulin (18.2%)." (PMID 24489845, 2014). "Therefore, both the assessment of insulin-secreting ability in individuals without diabetes and the stricter prevention of IR increases in those with low insulin-secreting ability will be necessary for the prevention of type 2 diabetes in Japanese individuals." (PMID 25166121, 2014). "Another study on diabetes patients without thyroid disorders showed treatment failure to sulfonylureas after a mean of 8.7 years in contrast to our group 1 and 2 patients who required insulin considerably earlier." (PMID 24580798, 2014). "In agreement with our hypothesis, we showed that fasting insulin levels in NOD mice that had not progressed to diabetes by 30 weeks were lower in GF versus CONV-R mice despite similar fasting glucose levels." (PMID 25390735, 2014). "However, advanced age, chronic obstructive pulmonary disease, and insulin-treated diabetes mellitus have a negative impact on late survival among patients with BIMA grafts." (PMID 25238877, 2014). "In most studies examining placenta nutrient transport characteristics, the mode of diabetes treatment is not considered and the groups contain both diet and insulin treated women, which might influence the pathology." (PMID 25222554, 2014). "Because HSP90 may be involved in sustaining functional insulin signalling pathway in type 2 diabetic muscles and higher HSP90 levels can be a consequence of type 2 diabetes, our results are potentially important for the diabetes research." (PMID 24689038, 2014). "Mice lacking endothelial NO synthase (eNOS), a key source of NO in vivo, are insulin resistant, have impaired fatty acid oxidation and display exaggerated high fat diet (HFD)-induced weight gain, and, the abundance of eNOS is remarkably diminished in obesity and diabetes." (PMID 25505420, 2014). "Our current data showed that a 4-month treatment with insulin glargine or NPH insulin significantly increases the ex vivo differentiation of EPCs in patients with type 2 diabetes mellitus, compared to an escalation of the oral antidiabetic therapy without additional insulin treatment." (PMID 25300286, 2014). "Likewise BCL11A, a human orthologue of CG9650, has been associated with type 2 diabetes mellitus, but prior work has not linked BCL11A to insulin regulation in mammals." (PMID 25101872, 2014).
diabetes (continued). "The second group of six subjects had no history of ketoacidosis but required insulin for the normalization of blood sugar while the third group were eight non- insulin dependent subjects with no history of ketoacidosis and were treated with diet and oral glucose lowering agents." (PMID 25945127, 2014). "In diabetes mellitus because of the absence of or insufficient sensitivity to insulin, glucose transporter protein in cell membrane called glucose transporter 4 is decreased and this problem leads to a decrease of glucose uptake by cells and therefore results in hyperglycemia." (PMID 24719730, 2014). "Thus, IG-1 has insulin-mimicking bioactivities and improves glucose tolerance in mice models of diabetes with or without obesity." (PMID 24971987, 2014). "In this controlled trial it was therefore studied, whether early addition of the long acting insulin analogue glargine or NPH-insulin are capable of increasing the number and differentiation of EPC compared to an escalation of oral diabetes medication after 4 months of treatment." (PMID 25300286, 2014). "However, HbA1c and FPG, which are used for the diagnosis of diabetes mellitus or the assessment of glycemic controls, were mainly correlated only with other glycemic variables such as 1,5-AG and GA, not with insulin-related variables or adiponectin." (PMID 25177913, 2014). "RIP-SDF-1 transgenic mice expressing CXCL12 under the control of the insulin promoter, are to some extent protected against streptozotocin-induced diabetes, suggesting that CXCL12 agonists could provide beneficial effects in the treatment of diabetes." (PMID 24988468, 2014). "However, it is not clear that the combination therapy of glargine insulin and which OADs is effective and safe in reducing fasting glucose and HbA1C among type 2 diabetes mellitus with chronic hyperglycemic control." (PMID 24614911, 2014). "After further adjustment for diabetes, hypertension, smoking, and BMI, the relationship between hsCRP, insulin and MCVE were no longer significant, while the relationship between Lp(a), neopterin, NT-proBNP and sRAGE and MCVE remained statistically significant." (PMID 25531109, 2014). "We included both individuals receiving diabetes medications or not on medication, but we excluded people taking insulin, so our results may not extend to individuals using insulin." (PMID 24717684, 2014). "This insulin transport may be regulated by multiple factors, such as glucocorticoids, or in several pathophysiological situations, such as fasting and re-feeding, obesity, and hibernation, as well as during aging and in patients with diabetes mellitus (DM), and AD." (PMID 25346723, 2014). "In vivo research showed that UFA could alleviate insulin resistance and promote insulin secretion, while in vitro studies have revealed that omega-6 polyunsaturated fatty acid (PUFA) can prevent chemically induced diabetes and attenuate the oxidant stress that occurs in diabetes mellitus." (PMID 24405938, 2014). "We proposed that, as in other well-defined disorders of insulin action in younger women – polycystic ovarian syndrome (PCOS), premature adrenarche, and precocious puberty – Syndrome W was a precursor of metabolic syndrome and diabetes at an apparently early, optimal stage for intervention." (PMID 25259787, 2014). "The study showed that adaptation to diabetes could be influenced by some demographic factors: Economic status, Type of treatment [Require insulin injections or without insulin injections], life events and Previous experience of illness in the family." (PMID 24401490, 2014). "In the United Kingdom Prospective Diabetes Study (UKPDS), the annual rate of major hypoglycaemia, defined by symptoms requiring assistance from a third-party or medical intervention, ranged from 0.7% in patients treated with oral drugs to 1.8% in the insulin-treated patients." (PMID 24927961, 2014).
diabetes (continued). "Therefore despite reduced TCR diversity of Treg cells mice do not develop diabetes and we were unable to detect insulin B:9–23 specific T cells in the periphery." (PMID 25379761, 2014). "Similarly, a low incremental 30 min insulin response during the OGTT was found to be a predictor of the development of diabetes in Mexican Americans, independent of obesity and fasting insulin concentrations." (PMID 25166121, 2014). "Our results showed that the presence of insulin-treated diabetes mellitus in cats does not affect faecal microbiota composition, as evaluated by the UniFrac distance metric or by comparison of relative abundances of predominant bacterial taxa identified by sequencing of the 16S rRNA gene." (PMID 25279695, 2014). "Finally, as previous studies have shown that metformin, thiazolidinedies and insulin may affect the plasma ADMA levels, their use for control of diabetes might result in bias in this study." (PMID 25467091, 2014). "However, diabetes itself or diabetes treatment (insulin or metformin) was not of prognostic value in our cohort." (PMID 25266049, 2014). "Therefore, we only included two trials in persons without diabetes in our meta-analysis of the effects of fenugreek on fasting insulin." (PMID 24438170, 2014). "However, that study was small, involving only six patients, and there are no other reports describing the effects of bezafibrate on insulin sensitivity, assessed by glucose clamps, in patients with type 2 diabetes mellitus." (PMID 25360162, 2014). "In this study of new insulin users (average age, 60 years; average duration of diabetes, 8 years), treatment with glargine insulin did not increase incidence of cancers when compared with NPH users after adjusting for baseline cancer risk factors including BMI and smoking status." (PMID 25329887, 2014). "The results indicated that insulin upregulates the mechanosensitivity of osteoblasts via the ERK pathway, which suggests that the mechanical sensitivity of bone may be reduced in patients with type 1 diabetes mellitus." (PMID 24348809, 2014). "The most important risk factors in our population to develop glucose intolerance or diabetes postpartum were a higher BMI at first prenatal visit, higher glucose values on the GCT and OGTT during pregnancy, an earlier diagnosis of GDM, and the need for bolus-basal insulin injections." (PMID 25180037, 2014). "However, antibodies, including ICAs, anti-GAD65, anti-IA-2, and anti-insulin, are absent in fulminant type 1 diabetes mellitus." (PMID 24711923, 2014). "These previous studies focused on diabetes patients and did not included non-diabetes subjects, moreover, many diabetic patients were treated with insulin and insulin per se could inhibit oxidative stress." (PMID 25013458, 2014). "The increase in insulin sensitivity occurs in women with PCOS without diabetes." (PMID 25069836, 2014). "For example: “Taking insulin means I have failed to manage my diabetes with diet and tablets”." (PMID 24902877, 2014). "While preaching prevention and proper management of diabetes, government and non-governmental agencies alike should also seek ways of subsidizing the cost of insulin and insulin analogues just as it is done for other epidemics; a level which diabetes is approaching." (PMID 24397956, 2014). "606/7753 (7.8%) of had diabetes; 98 were insulin-dependent and 508 were not." (PMID 24919660, 2014). "In contrast, for patients who had been undergoing insulin therapy, although a significant difference between the treatment and non-treatment groups was seen in the psychological impact of diabetes scale and HbA1c, the non-treatment group showed better scores than the treatment group." (PMID 25183994, 2014). "The NAVIGATOR study, a large international placebo-controlled trial, did not demonstrate the validity of nateglinide (a short-acting insulin secretagogue) for reduction of the incidence of diabetes and cardiovascular events in the patients of impaired glucose tolerance." (PMID 24843385, 2014).
diabetes (continued). "Diabetes mellitus is a group of metabolic diseases in which a person has high blood sugar, either because the body does not produce enough insulin or because cells do not respond to the insulin that is produced." (PMID 24971093, 2014). "However, our data suggest that diabetes in the absence of insulin therapy should not deter a surgeon from pursuing a BIMA revascularization strategy." (PMID 25238877, 2014). "Evidences have provided that after a period of poor glucose control insulin or diabetes drug treatment fails to prevent the development and progression of DR even when good glycemic control is reinstituted (glucose normalization), suggesting a metabolic memory phenomenon." (PMID 25165577, 2014). "The microbiome of the ileum in insulin-treated diabetes resembled the colon community and insulin could not restore the control microbiota in either GI segment." (PMID 25469509, 2014). "Despite this increased fracture rate, individuals with diabetes (insulin-dependent or non-insulin-dependent) were less likely to be on bisphosphonate therapy at any point over 10 years of prospective follow up compared to other CaMos subjects (odds ratio [OR]: 0.59; 95% CI 0.46-0.75, p < 0.001)." (PMID 24919660, 2014). "In a weight loss context, Shai and collaborators have observed decreases in both glucose and insulin concentrations in individuals characterized by type 2 diabetes mellitus with the adoption of the MedDiet whereas only reduced insulin concentrations were found in nondiabetic individuals." (PMID 25371817, 2014). "Web-based diabetes simulators, such as AIDA online, could conceivably be used in such skills-based training programmes to aid understanding of the relationships between insulin dose/timing and meal content/timing." (PMID 24511312, 2014). "Moreover, the inhibition of progression of diabetes in JTT-130 and combination groups might induce the increases of body weight and blood insulin level after day 20 of treatment." (PMID 24772450, 2014). "Therefore, the differences in quality of life attributable to retinopathy cannot be quantified without taking into account the impact of diabetes duration and insulin therapy." (PMID 25138117, 2014). "Although not always the case, pathologies such as diabetes and obesity may result from positive energy balance, a net surplus of hormones (e.g., insulin), and/or growth dysregulated factors (e.g., IGF), thereby increasing the risk of fetal overgrowth." (PMID 25222554, 2014). "Our model of prolonged equine hyperinsulinemia is unique in that it facilitates investigation of the effects of hyperinsulinemia in insulin-sensitive, non-obese individuals from a species that is prone to the development of metabolic syndrome, but not diabetes mellitus or cardiovascular diseases." (PMID 25101057, 2014). "Ketosis-prone diabetes is another form of diabetes that can appear to remit, with patients developing episodes of acute hyperglycaemia and ketosis, requiring insulin and intermittent periods with no insulin-dependence." (PMID 24909320, 2014). "Interestingly, persons without family history of diabetes revealed stark correlation of rs2241766 SNP, obesity, and insulin sensitivity among German people, making the role of ADIPOQ gene in T2DM controversial." (PMID 25121131, 2014). "After FC I/R injury, in the contralateral cerebral hemisphere, diabetes significantly reduced peroxynitrite levels compared with non-diabetic controls, whereas treatment with insulin showed a significantly higher peroxynitrite levels compared with the non-treated diabetic group." (PMID 25223305, 2014). "Diabetes mellitus should be managed by initiation of medical therapy with metformin and staged treatment intensification with a dipeptidyl peptidase-4 inhibitor, with a switch to a GLP-1 receptor agonist and initiation of insulin, as required, to achieve and maintain glycemic control." (PMID 23564338, 2014).